EGF (epidermal growth factor)
Diseases named in the same sentence as EGF in open-access papers (continued):
Sharing a sentence is not in itself a finding about the gene and the disease.
tumor (continued). "Studies demonstrated that not only the EGFR B cell epitopes consisted of residues from EGFR contacting sites with EGF, but also the combination treatments of peptide vaccines exhibited significant anti-tumor effects in vitro or in vivo." (PMID 27659529, 2016). "These include the COX-2, the tumor EGF, the angiogenic VEGF, other proangiogenic factors, and a large variety of chemokines and cytokines that amplify the inflammatory state." (PMID 28053982, 2016). "Epidermal growth factor (EGF) is the first ligand that is used to improve tumor cells specificity of SubA for the overexpression of epidermal growth factor receptor (EGFR) on tumor cell surface." (PMID 27585649, 2016). "The invading distance of furthest distal cells from the microposts were compared daily demonstrating that by days 3 and 4, the (+) EGF tumor invaded further than (−) EGF." (PMID 27678304, 2016). "Epidermal growth factor (EGF) is a well-known tumor promoter that has been widely used to induce cell transformation." (PMID 27447744, 2016). "Numerous modifications of polymers have been discovered to target tumor cells including folic acid, transferrin, epidermal growth factor (EGF) and the tripeptide arginine-glycine-aspartate RGD." (PMID 27735873, 2016). "Cancer cells were compartmentalized within our platform to represent a tumor surrounded by a stromal matrix where biochemical cues (i.e. EGF) diffused from outside of the stoma toward the center of the tumor region." (PMID 27678304, 2016). "We also calculated the progress of the tumor invasion front over the four day period for both conditions and found that by days 3 and 4, the (+) EGF tumor invaded further than (−) EGF." (PMID 27678304, 2016). "VEGF-A, FGF-2 and EGF, factors which characterize the angiogenic milieu, were able to significantly increase trypsinogen 4 expression by tumor-EC." (PMID 26318044, 2015). "Another study showed that annexin A8, which is highly expressed in CCs but downregulated upon tumor dedifferentiation, is downregulated by activation of the EGF/EGFR system via PI3K and Akt and that this correlated with EMT in CC cells." (PMID 26729094, 2015). "Previous studies have shown that tumor associated macrophages express a wide range of molecules, such as TGF-β, arginase-1, EGF, VEGF and IL-10." (PMID 26509874, 2015). "The tumor cell transformation induced by EGF was repressed by COX-2 knockdown, and this repression was reversed by simultaneously treating the cells with EGF and prostaglandin E2 (PGE2)." (PMID 25595899, 2015). "Fibronectin expression, activation of the FAK/Rac1/cdc42 axis downstream of fibronectin, and tumor migration were concomitantly induced by EGF." (PMID 25595899, 2015). "There are many cytokines secreted by aHSCs that are associated with tumor invasion and metastasis, including HGF, EGF, IL-1, IL-2, IL-6, MMP-2, MMP-9, TGF-β, TNF-α, VEGF and members of the Wnt signaling family." (PMID 26517671, 2015). "Specifically, EGF can activate ERα via serine phosporylation and promotes transcription of genes associated with aggressive HER2 positive tumours." (PMID 26215677, 2015). "We also provide evidence demonstrating that EGF activation induced the COX-2-primed tumor cell metastatic seeding of the lungs." (PMID 25595899, 2015). "The patients with tumor displaying the phenotype EGFR+/EGF+ had a significantly impaired OS compared to those with EGFR+/EGF− (48.1% versus 84.2%; p < 0.000; Fisher's exact test)." (PMID 26634172, 2015). "Following immunomagnetic sorting with CD133 beads, CD133+ tumor cells were cultured in serum-free DMEM-F12 medium supplemented with 20 ng/ml EGF and 10 ng/ml bFGF, and analyzed using flow cytometry (EPICS XL flow cytometer; Beckman Coulter)." (PMID 25435932, 2015). "Epidermal growth factor (EGF) is another carcinogenesis promoter, which induces tumor transformation through overexpression and activation of EGF receptor (EGFR)." (PMID 25874926, 2015).
tumor (continued). "This interaction is modulated by EGF/Src signaling, which triggers a tyrosine phosphorylation cascade that regulates tumor proliferation, migration, and invasion as well as metastasis in vitro and in vivo." (PMID 26549523, 2015). "Our in vitro experiments were conducted in serum-free conditions which selects for stem-like tumor cells with the addition of EGF and FGF." (PMID 25748921, 2015). "Our previous results have demonstrated that magnolin targeting ERK1 (IC50 87 nM) and ERK2 (IC50 16.5 nM) inhibits cell transformation induced by tumor promoters such as epidermal growth factor (EGF)." (PMID 26253302, 2015). "Disruption of CD151 or α3β1 integrin markedly impairs EGF/EGFR-evoked tumor cell motility and invasiveness." (PMID 26377974, 2015). "It's well-known that activation of STAT3 culminates in the transcription of its target genes and that EGF signaling relevant to tumor growth and metastasis is partially mediated by JAK1/2 phosphorylation." (PMID 25915156, 2015). "Intriguingly, complete ablation of mitochondrial butyryl coenzyme A synthetase 1, a GTP-dependent lipoate-activating enzyme was observed in tumours of EGF transgenic mice." (PMID 25872475, 2015). "It is synthesized by hepatocytes and an essential blood coagulation factor with all polypeptide chains being highly regulated in tumours of EGF transgenic mice." (PMID 25872475, 2015). "Using tail vein injection in an animal model, EGF-primed tumor cell metastatic seeding of the lungs was significantly inhibited with the depletion of COX-2 expression." (PMID 25595899, 2015). "One possible reason for the loss of EGFR amplification in vitro in addition to the growth pattern in vitro (adherent versus spheroid) is the propagation of tumor-derived cells in the presence of exogenous mitogens, especially EGF." (PMID 26136784, 2015). "A number of studies have established that tumors can actively induce tumor-associated lymphangiogenesis by secreting appropriate growth factors such as vascular endothelial growth factor- (VEGF-) C, VEGF-D, or VEGF-A and EGF." (PMID 25699271, 2015). "We focused on the secretion of EGF, HGF and IL6, because these soluble factors have been associated with an important role in tumor progression, resistance and inflammation." (PMID 26053043, 2015). "Although growth factors like EGF can activate the tumor-promoting function and the environmental stress like UV can activate the cell death pathway, the molecules in making this decision is nevertheless not determined." (PMID 26560124, 2015). "EGFR and HER2 are the members of the HER family, whose EGF signaling pathway has been shown to play an important role in tumor initiation, progression and metastasis." (PMID 26490766, 2015). "Medulloblastoma cell lines are most sensitive to exogenous HGF (4 out of 5 cell lines), FGF-2 (3 out of 5 cell lines) and EGF (3 out of 5 cell lines) resulting in increased tumor cell growth." (PMID 26496080, 2015). "To further confirm the function of fibronectin for tumor invasion in EGF-treated cells, we study the transendothelial invasion in EGF- and PTX3-treated fibronectin knockdown cells." (PMID 25797258, 2015). "Our recent study provided evidence indicating that RSK2 plays an important role in cell transformation induced by tumor promoters such as EGF and TPA." (PMID 26083344, 2015). "As a positive control to demonstrate that tumor cells were viable and responsive, they were stimulated with a cocktail of known tumor growth factors consisting of EGF, HGF, and IGF-1." (PMID 25807104, 2015). "In a human intrahepatic CC cell line, downregulation of miR-376c, which is suggested to function as a tumor suppressor, accelerated EGF-dependent migration through its direct target growth factor receptor bound protein 2 (GRB2)." (PMID 26729094, 2015). "Various tumor promoters, such as EGF, TPA, or UVC and oncogenes have been showed to induce activation of MSK1." (PMID 25958199, 2015).
tumor (continued). "Tumor spheres which have been derived from cultured cells in serum-free medium in the presence of bFGF and EGF, were found to be rich in cancer SLCs." (PMID 25760394, 2015). "Epidermal growth factor is a mitogen for hepatocytes, and plays a critical role in liver tissue regeneration, malignant transformation, tumor growth and progression." (PMID 25927412, 2015). "Tumor cell migration toward TMEM in vivo occurs in association with macrophages and involves epidermal growth factor (EGF)/colony stimulating factor 1 (CSF-1) paracrine signaling." (PMID 26112005, 2015). "These adhesion molecules also formed tight protein complexes and synergized with EGF/EGFR to accelerate tumor cell motility and invasion." (PMID 26377974, 2015). "Numerous wound and tumor-associated cytokines and growth factors promote HA synthesis, including TGFβ, PDGF, FGF2, EGF, and TNFα [Ref." (PMID 26106384, 2015). "The inhibition of this tumor-endothelial cell interaction in shCOX-2 cells was reversed when cells were treated with both EGF and PGE2." (PMID 25595899, 2015). "Consistent with what was observed in the transendothelial invasion assay, depletion of PTX3 inhibited metastatic seeding of EGF-primed tumor cells in the lungs." (PMID 25797258, 2015). "The inhibition of this tumor-endothelial cell interaction was rescued when PTX3-knockdown cells were treated with EGF and PTX3." (PMID 25797258, 2015). "In many tumors, molecules such as HGF, EGF, PDGF, and TGF-β are produced from the tumor-associated stroma and act as EMT-inducing signals." (PMID 26694366, 2015). "Trypsinogen 4 expression was upregulated by the combined action of VEGF-A, FGF-2 and EGF, angiogenic factors representative of the tumor microenvironment." (PMID 26318044, 2015). "In contrast, expression levels of certain miRNAs are tightly regulated during the cellular response to hypoxia in poorly differentiated solid tumors, and indeed EGF acts as an inhibitor to decrease the levels of tumor-suppressor miRNAs." (PMID 26528854, 2015). "The tail-vein injection animal model revealed that depletion of PTX3 decreased EGF-primed tumor cell metastatic seeding of the lungs." (PMID 25797258, 2015). "It is of considerable importance that gene expression of S100a4 and S100a11 was up to 34-fold induced in tumours of EGF transgenic mice, however expression of S100a1 was repressed." (PMID 25872475, 2015). "More specifically, we found that expression of MMP-9 in stromal was repressed by the activation of the EGR1 gene induced by EGF secreted by tumor cells and it correlates with decreased MMP-9." (PMID 25897433, 2015). "Another postulated mechanism is the action of epidermal growth factor, transforming growth factor-alpha and insulin-like growth factor secreted by the tumour cells themselves, which can lead to the cutaneous changes." (PMID 26152120, 2015). "Experimental models suggest that cancer cells release factors such as CSF-1, which stimulate macrophages in the tumor microenvironment and release EGF promoting tumor proliferation." (PMID 24879524, 2014). "This clone of JB6 cells is sensitive (P+) to tumor promoters like EGF or 12-O-tetradecanoylphorbol-13-acetate (TPA) and shows neoplastic transformation and anchorage independent colony formation upon stimulation with these agents." (PMID 25215281, 2014). "Activation of NF-κB and AP-1 is centrally involved in the induction of the MMP-9 gene associated with the invasion and metastasis of tumor cells by different agents, including TPA and growth factors, such as EGF." (PMID 24433534, 2014). "Under hypoxic conditions, silencing of HIF-1β expression suppressed tumor cell growth and regulated the expression of tumor growth-related factors, such as vascular endothelial growth factor, epidermal growth factor, and hepatocyte growth factor." (PMID 25068796, 2014). "VEGF, bFGF, epidermal growth factor (EGF), PDGF, and TGF-α, can also be produced by tumor associated macrophages." (PMID 24563633, 2014).
tumor (continued). "We cultured and expanded short-term tumor neurospheres in serum-free stem cell media, (supplemented with EGF and FGF), that were derived from four primary GBM patients, (i.e., PBT003, PBT008, PBT022 and PBT030)." (PMID 24732116, 2014). "It has been reported that endogenous RHBDL2 in tumor cell lines can activate the EGFR through the release of EGF." (PMID 24977233, 2014). "Memo knock-down (KD) tumor cells showed decreased migration following treatment with epidermal growth factor (EGF), heregulin (HRG) or fibroblast growth factor (FGF)." (PMID 24714781, 2014). "Growth factorssuch as the epidermal growth factor bind to these receptors in their extracellularbinding domain and start cascades of intracellular signaling that lead to tumor cellproliferation, migration, invasion, resistance to apoptosis and angiogenesis." (PMID 25004291, 2014). "EGF activates several pro-oncogenic intracellular pathways leading to tumor cell proliferation, cell cycle progression, angiogenesis and inhibition of apoptosis." (PMID 25909813, 2014). "Internalization of EGFR/ligand (EGF or anti-EGFR antibodies) complex is a physiological mechanism affecting the tumor cell response to growth and inhibition stimuli." (PMID 25238453, 2014). "EGF was found to facilitate DNA synthesis, regeneration, tumour growth and progression of HCC cells, and bind with EGFR as the potential connection between inflammation and HCC and one of therapeutic opportunities 3,10." (PMID 24268047, 2014). "At the molecular level, IQGAP3 interacts with ERK1 and promotes EGF-induced activation of ERK, which in turn appears to be closely associated with its tumor-promoting activity." (PMID 24849319, 2014). "Surprisingly, mostly CXCL447–70 exerted an anti-tumoral effect on EGF-dependent MDA-MB-231 tumor growth in vivo." (PMID 25373734, 2014). "Previous studies have shown that epidermal growth factor (EGF) +61 A/G polymorphisms are associated with cancer susceptibility and EGF tumor expression." (PMID 24516537, 2014). "Src seems to be activated when epidermal growth factor signaling is elicited, resulting in enhanced tumor progression and invasion." (PMID 24465609, 2014). "Here, we further explored the qualities of the carboxy-terminal peptides CXCL447–70 and CXCL4L147–70 as anti-tumoral agents, more specifically against a human epidermal growth factor (EGF)-dependent tumor cell line, MDA-MB-231." (PMID 25373734, 2014). "The miRNA and mRNA expression profiles of the primary cultures treated with TSH or with EGF/serum and the tumor tissues can be represented on a PCA (Principal Component Analysis)." (PMID 25375362, 2014). "Briefly, upon dissociation, tumor cells were cultured in suspension with EGF and FGF (20 ng/ml each) and allowed to form tumorspheres." (PMID 25541984, 2014). "Recently, we demonstrated that transforming growth factor β (TGF-β)–induced EMT empowers BCs with the ability to invade in response to paracrine epidermal growth factor (EGF) stimulation, thereby facilitating the egress of BC cells from the primary tumor." (PMID 24618085, 2014). "On contrary, GPRC5A-4 F, in which the four tyrosine residues have been replaced with phenylalanine, was resistant to EGF-induced phosphorylation and maintained tumor suppressive activities." (PMID 25311788, 2014). "Stimulation of tumor cells with EGF leads to phosphorylation of serine residues 405 and 418, coincident with a characteristic shift in cortactin electrophoretic mobility from 80 to 85 kDa in SDS-PAGE." (PMID 24971065, 2014). "So, it is remarkable that by virotherapy with Vaccinia virus endogenous EGF levels are reduced possibly resulting in inhibition of downstream pro-survival signaling pathways or inhibition of tumor cell invasion." (PMID 25030093, 2014). "EGF was detected in normal and tumoral breast tissues, with a higher expression found in normal tissues adjacent to tumor." (PMID 25249538, 2014).
tumor (continued). "To explore the diversity and consistency of the signaling pathways that regulate tumor cell migration, we chose three human tumor cell lines that migrated after treatment with EGF." (PMID 24820097, 2014). "Mechanistically, tumor cells synthesize CSF-1 in order to promote macrophage migration and macrophage-derived epidermal growth factor (EGF) enhances tumor cell invasion." (PMID 25125485, 2014). "Given the strong correlation with EGFR expression, it is conceivable that EGF signalling induces ZEB1 in these tumours." (PMID 23818228, 2013). "In the present study we describe the production of the human EGF derivative, EGFt, which lacks the eight final C-terminal amino acids of EGF in order to preserve the EGF high affinity for the receptor and the anti-tumour properties of PCI." (PMID 23935985, 2013). "The tumor cells used in this study (MCF-7 cells) are known to be sensitive to TNFα-induced cytotoxicity; accordingly, approximately 40% of the tumor cells were killed in vitro by their exposure to the combined stimulation of TNFα + Estrogen + EGF." (PMID 24369447, 2013). "EGF promotes tumor development amplifying the expression its tyrosine kinase epidermal growth factor receptor (EGFR) by increasing ligand-activated signaling through of its own receptor." (PMID 24294521, 2013). "To clarify the potential cross-talk and feed-back regulation between tumor cells and cytokines in surrounding microenvironments, we investigated the expression of cytokines induced by EGF in squamous cancer cells." (PMID 23383347, 2013). "Our data highlight the complex interrelationship between tumour hypoxia, EGF and angiogenesis in the pathogenesis of CRC." (PMID 24180698, 2013). "Reversion-inducing cysteine-rich protein with Kazal motifs (RECK) is a tumor suppressing, membrane-anchored glycoprotein that contains multiple epidermal growth factor-(EGF)-like repeats and multiple serine protease inhibitor-like domains." (PMID 24376819, 2013). "EGF is known to induce tumor cell invasion and affect fibroblast migratory characteristics in conventional cell culture and 3D-hydrogels." (PMID 23671660, 2013). "Already at the initial phases of the study we found that the combined stimulation had a much higher influence than TNFα alone, estrogen alone, or EGF alone on the tumor-promoting aspects that were studied." (PMID 24369447, 2013). "Two different modes of molecular regulation initiated by the HH/EGF cross talk were identified, with relevance for tumor initiation and tumor progression." (PMID 23762360, 2013). "EGF-SubA significantly potentiated PDT-mediated cytotoxicity in five different human tumor cell lines, which was accompanied by a specific GRP78 cleavage." (PMID 23887632, 2013). "The interaction of HH/GLI with EGF-induced signaling has been described in a number of tumor types such as skin, prostate, and pancreas, while other kinases such as PKC and mTOR/S6K also positively regulate GLI activity." (PMID 23762360, 2013). "Based on these findings, we suspect that mTOR complex components and their interacting molecules are convergent targets of tumor-suppressive microRNAs controlled by oncogenes, such as Src and EGF." (PMID 24244675, 2013). "When used singly, TNFα was more effective than the other two representatives of the tumor microenvironment—estrogen and EGF—and its activities were potently increased by cooperating with these two factors." (PMID 24369447, 2013). "EGF plays a central role in cancer development since it is involved in crucial steps of tumor progression such as proliferation, angiogenesis, invasiveness, decreased apoptosis, and loss of cellular differentiation." (PMID 24294521, 2013). "For instance, Hedgehog (HH)/GLI and EGF-driven signaling can synergize and promote events, such as neural stem cell proliferation, as well as tumor initiation and progression." (PMID 23762360, 2013).